TET2 (tet methylcytosine dioxygenase 2)
Diseases named in the same sentence as TET2 in open-access papers (continued):
Sharing a sentence is not in itself a finding about the gene and the disease.
myelodysplastic syndrome (continued). "In particular, alterations in TET2—a regulator of cytosine methylation—have been detected frequently in myelodysplastic syndromes (MDS) and more recently have been reported to occur as secondary cytogenetic abnormalities in acute and blast phase CML." (PMID 22467334, 2012). "TET2 was first identified as a tumor suppressor gene in myelodysplastic syndrome." (PMID 35480097, 2022). "Moreover, patients with myelodysplastic syndrome (MDS) aged > 65 years and harboring TET2, DNMT3A, and AXSL1 mutations were susceptible to PAD and systemic inflammation." (PMID 34943774, 2021). "TET2 mutations predict responses to HMAs in myelodysplastic syndrome (MDS); however, this has not been substantiated in AML." (PMID 34070172, 2021). "Somatic TET2 mutations were first reported as present in ~15% of myeloid cancers, with the loss of function mutations in TET2 accounting for approximately 10% of newly onset AML, 50% of CMML, and approximately one‐third of all mutations in myelodysplastic syndromes." (PMID 36618446, 2021). "Interestingly, one of the somatic TET2 mutations we found (c.4045-1G > A; ATL07) was previously identified in myelodysplastic syndromes." (PMID 28881727, 2017). "Case LYWS-1389 (Erica Swenson) had a concurrent diagnosis of myelodysplastic syndrome (MDS) and AITL with a shared TET2 mutation, and with DNMT3A and RHOA mutations additionally identified only in the AITL component involving the pleural fluid." (PMID 37500795, 2023). "TET2 mutations are commonly identified in myeloid and lymphoid malignancies and are amongst themost recurrently acquired mutations identified in patients suffering from chronic myelomonocytic leukaemia (CMML, 50–60%), AML (~20%), and myelodysplastic syndromes (MDS, ~20%)." (PMID 36989121, 2023). "However, compared with conventional myelodysplastic syndromes, these cases displayed a paucity of somatic mutations in DNMT3A (2 of 41) and TET2 (3 of 41 cases), suggesting that evolutionary paths may differ between cases with long versus short telomeres." (PMID 35835912, 2022). "Of these non-JAK2 mutation cases, the NRAS, CSF3R and TET2 c.4319_4329del; p.Arg1440Hisfs*34 were in the context of therapy-related disease; the remaining 4 other mutations (TET2, TET2, DNMT3A, and SF3B1) were in the context of disease progression from myelodysplastic syndrome." (PMID 36323674, 2022). "Data from a recent meta-analysis has shown that in spite of the fact that TET2 mutations had no significant prognostic value on myelodysplastic syndromes, the response rates to hypomethylating agents were significantly different between patients with and without TET2 mutations." (PMID 35386689, 2022). "TET2 mutations are frequent in patients with AML, myelodysplastic syndromes (MDS) and chronic myelocytic leukaemia (CML), while TET1 and TET3 mutations are rare." (PMID 34656178, 2021). "Additionally, mutant U2af1 combined with Tet2-deficiency does not suffice to initiate myelodysplastic syndrome." (PMID 34203454, 2021). "TET2 mutations frequently occur in AML, myelodysplastic syndromes (MDS) and chronic myelomonocytic leukemia (CMML), whereas TET1 and TET3 mutations rarely happen." (PMID 32209730, 2020). "Moreover, TET2 mutations were important prognostic factors in AML and predicted response to hypomethylating agents in Myelodysplastic syndromes (MDS) patients." (PMID 36371552, 2023). "Similarly, TET2 mutant bone marrow cells from myelodysplastic syndrome (MDS) subjects are resistant to the suppressive effects of TNF-α on colony formation." (PMID 32722135, 2020).
myelodysplastic syndrome (continued). "However, a major subset of myelodysplastic syndromes (MDS) cases harboring wild type (WT) TET2 show significantly lower global 5hmC levels than do healthy donors, suggesting that other factors regulate TET2 function, such as protein acetylation, as reported in our previous study." (PMID 32726753, 2020). "In addition, TET2 mutations are an unfavorable prognostic factor in AML and are associated with increased response to hypomethylating agents in myelodysplastic syndrome (MDS)." (PMID 31097014, 2019). "Importantly, in other studies in breast cancer and myelodysplastic syndrome (MDS), it was suggested that miRNA-mediated TET2 repression contributes to tumorigenesis." (PMID 28783103, 2017). "However, miR-22 is also an epigenetic modifier that promotes stemness and metastasis of myelodysplastic syndrome (MDS) and breast cancer by targeting TET2." (PMID 27811373, 2016). "Among TET genes, alterations in TET2 are frequently reported in myeloid disorders, occurring in 10% of de novo AML, 30% of myelodysplastic syndrome (MDS) and almost 50% of chronic myelomonocytic leukemia (CMML) cases." (PMID 35938170, 2022). "In myelodysplastic syndrome (MDS) and AML cells, HDAC4 inhibition leads to the downregulation of TET2 and the subsequent decrease in the abundance of 5hmeC marks." (PMID 33805247, 2021). "Moreover, loss-of-function mutations in TET2, which impair its catalytic activity, are often observed in patients with chronic myelomonocytic leukemia (CMML), myeloproliferative neoplasms (MPN), myelodysplastic syndrome (MDS), as well as B cell and T cell lymphomas." (PMID 25557833, 2015). "Thus, in addition to providing BM radiation resistance, CR or CR mimetics may provide an advantage for non-cancerous TET2 WT BM HSPCs to compete against enzyme inactive TET2 mutant HSPCs, potentially limiting aplastic anemia and/or myelodysplastic syndromes." (PMID 35406143, 2022). "Differently from myelodysplastic syndrome (MDS), their efficacy in AML is independent of the mutational status of epigenetic modifiers such as IDH1, IDH2, DNMT3A and TET2." (PMID 34439275, 2021). "On the other side, ZFN-inactivation of tet2, a gene coding for one of the TET family members of DNA methylcytosine oxidases that converts 5-methylcytosine into 5-hydroxymethylcitosine during the DNA demethylation process, is responsible for generalized myelodysplastic syndromes (MDS) in zebrafish." (PMID 32759814, 2020).
myeloproliferative neoplasm (94 papers, 2010 to 2025). A clonal hematopoietic stem cell disorder, characterized by proliferation in the bone marrow of one or more of the myeloid (i.e., granulocytic, erythroid, megakaryocytic, and mast cell) lineages. "Dysfunction of TET2 can induce a hypercoagulable state, which is particularly prominent in patients with myeloproliferative neoplasms (MPNs), where TET2 mutations are frequently observed." (PMID 41169875, 2025). "The TET2 gene mutations have also emerged as a significant contributor to thrombosis in myeloproliferative neoplasms-a hematologic malignancy." (PMID 41169875, 2025). "The overexpression of Hmga2 induced a myeloproliferative phenotype in a transgenic mouse, and drove the development of myeloproliferative neoplasms induced by the JAK2V617F mutation or Tet2 deletion in mouse models." (PMID 38811851, 2024). "TET2 gene is one of the commonly found mutated genes in BCR-ABL-negative myeloproliferative neoplasms." (PMID 34203097, 2021). "The TET2 gene shows mutations in variable myeloid malignancies with the involvement of 15% of myeloproliferative neoplasms (MPNs)." (PMID 34660059, 2021). "The order in which somatic mutations are acquired determines how individual cancers behave, and the order in which JAK2 and TET2 are mutated influences clinical features and response to targeted therapy in patients with myeloproliferative neoplasms." (PMID 33653301, 2021). "After ruling out myelodysplastic and other myeloproliferative diseases the patient was finally diagnosed as aCML according to the WHO criteria with mutations in the TET2 gene, the NRAS gene and in the KRAS gene." (PMID 34840744, 2021). "For example, positions 123, 817, 1204, 1762 and 1811 of TET2 were inferred to be have undergone positive selection by the Fitmodel software program and located at natural variants found in myeloproliferative neoplasms." (PMID 26633372, 2015). "Loss-of-function TET2 mutations occur in patients with myeloproliferative neoplasms, MDS and AML, while upregulation of TET2-targeting miRNAs, such as miR-7, miR-29b, miR-29c, miR-101, and miR-125b, occur in AML patients with wild-type TET2." (PMID 25364765, 2014). "High-throughput DNA sequence analysis was used to screen for TET2 mutations in peripheral blood derived DNA from 97 patients with BCR-ABL-negative myeloproliferative neoplasms (MPNs)." (PMID 23781511, 2013). "TET2 has been found mutated in patients with myeloproliferative neoplasms (MPN), MDS, AML and chronic myelomonocytic leukemia (CMML), and is the most commonly mutated gene in MDS." (PMID 23634848, 2013). "Six years later, TET2 somatic mutations were identified in myeloproliferative neoplasms (MPN) and myelo-dysplastic syndrome (MDS)." (PMID 24202321, 2013). "This regulatory function suggests that TET2 mutations or dysregulation could predispose individuals to thrombotic events, particularly in conditions such as myeloproliferative neoplasms, where thrombosis risk is notably elevated." (PMID 41169875, 2025). "Therefore, this study aims to estimate the prevalence of TET2 gene mutations in myeloproliferative neoplasms." (PMID 34203097, 2021). "Prevalence of TET2 mutation in myeloproliferative neoplasms." (PMID 34660059, 2021). "Tet2 deficiency in mice recapitulated myeloproliferative disease (MPD) and lymphoma in humans." (PMID 33705482, 2021). "(2015) with respect to the order of JAK2 and TET2 mutations in myeloproliferative neoplasms." (PMID 29656894, 2018). "Similarly, our results also demonstrated age-related hypermethylation of TET2, a putative tumor suppressor gene that has recently been shown to be genetically mutated in myeloproliferative disorders." (PMID 20523906, 2010). "However, mutations which are reported to play a major role in myeloproliferative neoplasms, such as ten-eleven translocation-2 (TET2), runt-related transcription factor 1 isoform (RUNX1), janus kinase 2 (JAK2) V617F, and Soc-2 suppressor of clear homolog SHOC2 are not involved in JMML." (PMID 22162691, 2012).
myeloproliferative neoplasm (continued). "In studies of AMLs secondary to myeloproliferative neoplasms (MPN) mutations of TET2 have indeed been shown to occur early or late." (PMID 20678218, 2010). "TET2 mutations have also been reported in up to 28% of MDS and myeloproliferative neoplasms and up to 50% of angioimmunoblastic T cell lymphoma (AITL), where they are associated with poor response to anthracycline-based chemotherapy." (PMID 36480300, 2023). "Somatic variants were rarely identified with VAFs >=10% in nail samples and were primarily confined to disease-defining alterations associated with loss of heterozygosity (LOH) in the tumor sample, such as JAK2 and TET2 in myeloproliferative neoplasms." (PMID 37898613, 2023). "Like DNMT3A, TET2 is considered an early preleukemic mutation associated with the sequential acquisition of additional mutations in AML and myeloproliferative diseases." (PMID 38028538, 2023). "We examined AML-43 in detail, which was a case evolving from an antecedent JAK2 + TET2 + myeloproliferative neoplasm (MPN)." (PMID 34021247, 2021). "We next applied TARGET-seq to analyze 458 HSPCs in samples from five patients with myeloproliferative neoplasms (MPN); the samples carried different combinations of JAK2V617F, EZH2, and TET2 mutations." (PMID 30765193, 2019). "TET2 mutations were found in 17% of patients with MDS, 46% of MDS/myeloproliferative neoplasms, 19% of myeloproliferative neoplasms, 21% of primary AMLs and 20% of treatment-related myeloid neoplasia." (PMID 30813354, 2019). "We aimed to determine the genotype distribution, allele frequency, and prognostic impact of IDH1/2, TET2, and ASXL1 single nucleotide polymorphisms (SNPs) in myeloproliferative neoplasms (MPNs)." (PMID 28218607, 2017). "Mice with a targeted Flt3ITD mutation develop myeloproliferative neoplasms (MPN), and several other mutations (e.g. Npm1, Tet2 and Runx1 mutations) cooperate with Flt3ITD to drive AML in mice much as in humans." (PMID 27879203, 2016). "TET2 mutations are observed in a range of myeloid neoplasms including AML, MDS, and myeloproliferative neoplasm (MPN)." (PMID 27023522, 2016). "Mutations in TET2 have been found in a range of hematological malignancies, including AML, MDS, myeloproliferative neoplasms (MPN), and chronic myelomonocytic leukemia (CMML) with frequencies of 24%, 19%, 12% and 22%, respectively." (PMID 27329599, 2016). "Mutations of EZH2, TET2, IDH1/2, and DNMT3A involved in epigenetic regulation are frequently observed in adult AML, MDS, and myeloproliferative disease (MPD)." (PMID 25914884, 2015). "They identified inactivating mutations of the TET2 gene in about 15% of patients with various myeloid malignancies, such as MDS (19%), myeloproliferative disorders (12%), secondary AML (24%) and chronic myelomonocytic leukemia (CMML) (22%)." (PMID 21917154, 2011). "In another study, it was reported that mouse models of CH carrying mutations in Tet2, Dnmt3a, Asxl1, and Jak2 demonstrated that obesity accelerated the size of CH clones and increased the risk of developing a myeloproliferative neoplasm (MPN)-like phenotype, regardless of the specific mutation." (PMID 39119355, 2024). "In some patients with myeloproliferative neoplasms (MPN), two genetic mutations are often found: JAK2 V617F and one in the TET2 gene." (PMID 38363386, 2024). "TET2 LOF mutations were found in ~20% of MDS patients, ~20% of myeloproliferative neoplasms (MPN), ~20% of AML, and ~45% of chronic myelomonocytic leukemia (CMML)." (PMID 36979633, 2023). "These NGS panels target genes that are associated with multiple hematological conditions, e.g., DNMT3A, TET2, ASXL1, and genes that are implicated in the pathogenesis of specific hematological disorders, e.g., JAK2 for myeloproliferative neoplasms (MPN)." (PMID 36290845, 2022).
myeloproliferative neoplasm (continued). "Here, the authors show that HOXA9 has a binary switch function that can clinically stratify AML patients, and model how the interactions with JAK2, TET2 and NOTCH impact myeloproliferative neoplasms." (PMID 36192425, 2022). "After follow up of seven TET2 mutant individuals for at least 5 years, one developed evidence of a haematological malignancy: a JAK2V617F mutant myeloproliferative neoplasm (MPN)." (PMID 25056697, 2014).
atherosclerosis (92 papers, 2016 to 2026). A disease characterized by the build-up of fatty material and calcium deposition in the arterial wall resulting in partial or complete occlusion of the arterial lumen. "Tissue-specific signatures of atherosclerosis-affected LAD coronary arteries were assessed in 26 TET2 CHIP CAD mutation carriers and 13 paired-matched controls without CHIP." (PMID 40900105, 2026). "Loss of endothelial-expressed TET2 correlates with atherosclerosis progression in vivo and alters vasoactive signaling in vitro." (PMID 40716745, 2025). "Another study in animal models reported that pharmacological inhibition of NLRP3 inflammasome in TET2-deficient mice resulted in decreasing the inflammatory state, lowering IL-1β, and ameliorating atherosclerosis and heart failure." (PMID 40804878, 2025). "Epidemiological studies address a link between TET2 mutations and an increased risk of AF, demonstrating associations between accelerated atherosclerosis, myocardial fibrosis, cardiac arrest, and adverse cardiac remodeling, with TET2 alterations." (PMID 40804878, 2025). "This link is reinforced by the transplantation of TET2-deficient bone marrow into atherosclerosis-prone mice, leading to an increase in plaque size, necrotic core formation, and vascular inflammation." (PMID 41458386, 2025). "It is still unclear if the beneficial effects of Tet2-mediated CH on stroke outcomes would differ in individuals with cardiovascular risk factors, particularly atherosclerosis and hypertension, which are aggravated by hematopoietic Tet2 mutations." (PMID 39742155, 2024). "Recently, we showed that HL and Abro1 deficiency decreased atherosclerosis in mice with TET2 CH in which the NLRP3 inflammasome is an important driver of disease." (PMID 38522750, 2024). "Even if these findings are secondary to TET2 loss in another cell type, they still have potential relevance to diseases regulated by IgMs produced by B-1 cells such as infection, atherosclerosis, and obesity-related metabolic dysfunction." (PMID 38601144, 2024). "Increased inflammasome activity associated with TET2 CHIP in mice has been linked to an accelerated development of atherosclerosis and greater cardiac dysfunction." (PMID 37947606, 2023). "The causal effect of both DNMT3A and TET2 loss-of-function within myeloid cells upon clonal expansion and the development of atherosclerosis has also been demonstrated unequivocally in atherosclerosis-prone mice." (PMID 37304954, 2023). "The NLRP3 inflammasome also plays a crucial role in mediating ten-eleven translocation 2 (Tet2) mutation, which participate in onset of atherosclerosis, which is further explained in the following section on aging." (PMID 37686238, 2023). "In this context, somatic mutations, particularly in DNA methyltransferase 3 alpha and TET methylcytosine dioxygenase 2, are also implicated in the pathogenesis of both atherosclerosis and DKD, partly by a pro-inflammatory effect." (PMID 36983082, 2023). "This is consistent with experimental studies showing a specific mechanistic connection between mutated TET2 and atherosclerosis." (PMID 36835370, 2023). "Somatic mutations in the gene encoding the TET2 enzyme promote clonal hematopoietic expansion and accelerate atherosclerosis in mice with hyperlipidemia." (PMID 36837885, 2023). "Tet2-deficient macrophages exhibit strong IL-1β secretion capacity and promote the formation and development of atherosclerosis in mice." (PMID 38012545, 2023).